MYC (MYC proto-oncogene, bHLH transcription factor)
Diseases named in the same sentence as MYC in open-access papers (continued):
Sharing a sentence is not in itself a finding about the gene and the disease.
leukemia (continued). "Strikingly, a significant positive enrichment for the MYC gene signature was apparent in Eμ-Crlf2/Jak2R683G leukemia cells with chronic Jak2 depletion across multiple data sets (FDR < 0.01)." (PMID 29907650, 2018). "An emerging group of NOTCH1-independent TAL/LMO-positive leukemias harboring MYC translocations (constituting around 1–6% of adult and childhood T-ALL cases) has been recently described." (PMID 30304769, 2018). "And this finding also provides us a promising therapy like the combination of R‐2HG and inhibitor of MYC signalling to cure leukaemia." (PMID 30039919, 2018). "Specifically, Wnt-activation has been previously shown to mediate the reactivation of MYC signaling in leukemia cells resistant to bromodomain inhibition." (PMID 29207623, 2017). "We observe a similar effect in our leukemia model, with MYC protein levels being disproportionately reduced when PVT1 is depleted." (PMID 28875933, 2017). "In accordance, a block to Pol II elongation in the endogenous MYC promoter induces transcriptional down-regulation of MYC and differentiation in human leukaemia cell lines." (PMID 28398229, 2017). "One important discovery in this study is that activation of the AKT pathway was acquired in a subset of the clones, and increased the number of leukemia-propagating cells through activating mTORC1 and elevated growth rate, probably by stabilizing MYC." (PMID 28930163, 2017). "Three ‘leukemia lncRNAs’ affect MYC and enforced expression of this oncogene rescues proliferation and differentiation effects." (PMID 28875933, 2017). "MYC promotes cell transformation not only through increased cell growth and proliferation but also sustaining leukemia-initiating activity." (PMID 28872614, 2017). "We show here that all of the Pu27 family members inhibit cell proliferation as much as, and in some cases even more than Pu27 in four different leukemia cell lines presumably through c-MYC downregulation." (PMID 27551915, 2016). "We have previously shown that Pu27 downregulates c-MYC expression and inhibits the growth of leukemia cell lines." (PMID 27551915, 2016). "c-MYC has been shown to be regulated by BRD4 in various cancer cell lines such as Hela cells and leukemia cells, and c-MYC expression was reduced upon BRD4 knockdown or cell treatment with small molecules inhibiting BRD4." (PMID 26830473, 2016). "The MYC enhancer interaction landscape in EBV-infected cells is therefore distinct from leukaemia cells, where downstream enhancers are the major controllers of MYC transcription." (PMID 27490482, 2016). "Several reports link S1P to leukemia and it has very recently been reported that sphingosine kinase plays an oncogenic role in acute lymphoblastic leukemia by regulating MYC expression." (PMID 26919114, 2016). "In support of this, concomitant NOXA and MCL1 upregulation is observed in MYC-driven leukemias, and following activation of RAS in epithelial cells." (PMID 26910119, 2016). "We have established that each oligonucleotide sequence of the Pu27 family forms a stable G-quadruplex structure, binds in a sequence specific manner to the NHEIII1 of the c-MYC promoter and inhibits cell growth of leukemia cell lines." (PMID 27551915, 2016). "These compounds were initially shown to be effective in the treatment of leukemia, lymphoma, and multiple myeloma, primarily as a result of repressing c-MYC expression." (PMID 27283767, 2016). "Consistent with our findings, leukemia cells have also been shown to upregulate c-MYC levels during the development of resistance to BET inhibitors." (PMID 27283767, 2016). "The expression of c-MYC in particular was found to contribute to leukemogenesis and promote the progression of leukemia." (PMID 26046133, 2015). "Since c-MYC is aberrantly expressed in a wide variety of human solid tumors as well as in leukemia, it is an attractive target for cancer therapy." (PMID 26046133, 2015).
leukemia (continued). "Together, these data support the role of JQ1 as an agent that lowers MYC protein levels and is thus able to inhibit growth of MYC-dependent leukemias, with an efficacy inversely correlated with MYC expression levels." (PMID 25956709, 2015). "The myeloid HL-60 leukemia cell line also underwent apoptosis by treatments that reduce c-MYC expression." (PMID 26472107, 2015). "In a T-ALL mouse model, MYC protein levels in leukemia-initiating cells were found to be heavily dependent on FBXW7 activity, demonstrating that MYC is the major contributor to the FBXW7 phenotype." (PMID 25669969, 2015). "We reasoned that removal of the powerful MYC oncogene would reveal the leukemia-initiating potential of additional cDNAs." (PMID 26606454, 2015). "Later on, mounting evidence has been accumulated showing that the c-MYC protein is a key player in hematopoiesis and leukemia." (PMID 26472107, 2015). "The appearance of PIM2 and MYC together in three different mice strongly suggests that the two proto-oncogenes synergistically stimulate leukemia development." (PMID 26606454, 2015). "To prove this point, we submitted graphical sequencing profile of the every cDNA band from Mouse #1 to Mouse #5 in the first set of experiment in which leukemia was initiated with retroviral cDNA library (including MYC)." (PMID 26606454, 2015). "Inactivation of c-MYC represents as a novel approach to improve clinical outcome and prognosis in leukemia treatment." (PMID 26472107, 2015). "The second experiment with MYC-deleted library showed that members of the homeobox gene family constitute another potent leukemia-inducing gene combination." (PMID 26606454, 2015). "Our second screen using the MYC-deleted proto-oncogene library confirmed MEIS1and the HOX family as cooperating oncogenes in leukemia pathogenesis." (PMID 26606454, 2015). "Up-regulated expression of c-MYC in leukemia cells promoted the colony formation ability and maintained poor differentiation leading to drug resistance." (PMID 26472107, 2015). "Since the strong cooperation of MYC and RAS has been reported before in various solid tumors, the MYC/KRAS combination observed in Mouse #10 most likely reflects the outcome of genuine cooperation between the two genes in leukemia induction." (PMID 26606454, 2015). "Second, two recent studies support the role for MYC in T-ALL leukemia initiation and demonstrate anti-leukemic activity with BET bromodomain inhibitors, including JQ1." (PMID 25072021, 2014). "In contrast, withdrawal of AZD1208 after 20 days of treatment results in relapse suggesting the myeloid cells that have survived are sufficient to recapitulate the leukemia in the presence of MYC." (PMID 25238262, 2014). "Preclinical evaluation of the Brd4 inhibitor JQ1 in AML demonstrated potent in vitro and in vivo inhibition of leukemia proliferation and elimination of leukemia-initiating cells, likely via suppression of MYC." (PMID 24672775, 2014). "Aggressive leukemia development requires the continued expression of MYC and the constitutive activity of PIM." (PMID 25238262, 2014). "This action causes the downregulation of BCL-2, MYC and CDK6, thereby inducing cell cycle arrest and apoptosis in leukemia models." (PMID 24576043, 2014). "The natural product bryostatin 1, a modulator of protein kinase C (PKC) activity, has been shown to affect MYC regulation in leukemias and neuroblastomas; therefore, we chose to study the activity of picolog in a MYC-induced neoplasm." (PMID 22308267, 2012). "In our study, MYC’s contribution as an individual marker was strong, achieving the highest AUC for the discrimination between leukemia vs. non-leukemia samples (AUC = 0.835), and second for leukemia + MRD-positive vs. non-leukemia + MRD-negative samples (AUC = 0.769)." (PMID 41596324, 2026).
leukemia (continued). "CCDC26, a long noncoding RNA located within the ~2 Mb MYC locus and frequently amplified in leukemia, has been shown to regulate acute myeloid leukemia cell proliferation through KIT signaling and to influence erythroid differentiation via FOG-2–mediated transcriptional control of globin genes." (PMID 41509392, 2025). "MYC is not activated by mutations in the coding sequence, but its overexpression in leukemia is mainly caused by gene amplification and aberrant regulation of its transcription." (PMID 39940843, 2025). "Therefore, a thorough understanding of the role of SETD1B-mediated H3K4me3 breadth is critical for developing markers and therapies for other leukemia subtypes and cancers dependent on MYC." (PMID 40341256, 2025). "Thus, a thorough understanding of SETD1B-mediated H3K4me3 breadth is critical for developing markers and therapies for MYC-dependent leukemia subtypes." (PMID 40341256, 2025). "Another proto-oncogene closely involved in many cancers, including leukemia, is MYC." (PMID 39940843, 2025). "Like MYC, MECOM is another transcription factor which can activate proliferation gene programs, and translocations of MECOM have recently been included as adverse risk factors in leukemia classification guidelines." (PMID 41008781, 2025). "We found that genes associated with HSCs and leukemia stem cells (LSCs) were up-enriched in high LAPTM4B expression samples, as well as genes associated with cell cycle, DNA replication, MYC target, E2F and G2M checkpoint pathways were also up-enriched in in Ph+ B-ALL." (PMID 40092987, 2025). "In addition, we observed downregulation of leukemia-associated proto-oncogenes such as CCND1/2 (0.46, p < 0.05), CCNE2 (0.38 p = 0.0076), MYC (0.42, p < 0.001), SRC (0.3, p < 10−5), or MPL (0.25, p < 0.05)." (PMID 41438051, 2025). "Employing the MAGeCK algorithm, this focused CRISPR screen unveiled COX4I1 (encoding Cytochrome c oxidase subunit 4 isoform 1) as a top essential gene in leukemia cells, alongside five previously reported leukemia essential genes (MYC, RPS6, CCND3, GAB2, and AURKB)." (PMID 39716856, 2025). "Interestingly, MS177, a recently developed EZH2‐specific PROTAC degrader by other groups,[13b] achieved effective depletion of both EZH2 and interacting partners MYC in leukemia." (PMID 39823459, 2025). "A gene regulated by super-enhancer that has a particular relevance in leukemia, is MYC." (PMID 39201306, 2024). "Furthermore, diclofenac inhibits leukemia cell proliferation by downregulating c-MYC gene expression." (PMID 38473997, 2024). "Collectively, our data highlight MGA as an important regulator of pathways critical for leukemia development, such as MYC activation, cell cycle, and oxidative phosphorylation, and that loss of function mutations identified in patients can functionally cooperate with the RUNX1::RUNX1T1 oncoprotein." (PMID 38454121, 2024). "Moreover, Mettl5 KO promotes leukemia growth by translationally inhibiting F-box and WD repeat domain-containing 7 (Fbxw7), a c-MYC degrader and a key regulator of cell differentiation." (PMID 39497033, 2024). "Additionally, the FTO/m6A/myelocytomatosis oncogene (MYC)/(CCAAT/enhancer binding protein α) (CEBPA) signaling pathway plays a crucial role in leukemia." (PMID 39295872, 2024). "Moreover, NSD3S has been shown to be sufficient for leukemia progression, it also stabilizes and increases MYC transcriptional activity and is present on the oncogenic NUT fusion." (PMID 38256018, 2024).
leukemia (continued). "In leukemia, oncogenic driver genes such as MYC and RAS alter metabolic pathways." (PMID 39767649, 2024). "MYC drives oncogenesis by promoting the expression of genes involved in cell growth, metabolism, and survival, making it an essential target for therapeutic intervention in these leukemias." (PMID 39682203, 2024). "Increasing global m6A RNA modification in leukemia cells could decrease the stability of MYC and result in the suppression of MYC pathways." (PMID 36743697, 2023). "However, numerous researches on WDR5 focus on its role as a bridge between the mixed lineage leukemia complex and oncoproteins like MYC." (PMID 38028543, 2023). "MYC can promote bone marrow stem cell dysfunction and leukemia stem cell self-renewal." (PMID 35794546, 2022). "Moreover, it increases m6A modification of RNA by inhibiting FTO activity, destabilizing CEBPA/MYC transcripts in leukemia cells." (PMID 35186927, 2022). "Similarly, it was found that the combination of inhibitors targeting PI3K/AKT/mTOR signaling pathway and atRA can almost eliminate cellular MYC to drastically kill leukemia cells of different AML subtypes." (PMID 35865470, 2022). "Spearman correlation analyses between UHRF1 mRNA levels and the gene expression of MYC family members (MYC, MYCN, and MYCL1), as well as CDK4 and CDK6 in the Haferlach and Gu leukemia datasets, indicated positive associations between UHRF1 and c-Myc, CDK4, and CDK6 in ALL." (PMID 36077796, 2022). "In addition, the metabolite R-2HG caused by isocitrate dehydrogenase (IDH) mutation exerts anti-leukemic effects by inhibiting FTO/m6A/MYC/CEBPA signaling, providing a new target for clinical dosing in the treatment of leukemia." (PMID 36118041, 2022). "BCR-ABL inhibits BGL3 expression via MYC-dependent DNA methylation and loss of BCR-ABL results in the increase of BGL3, decrease of MYC expression and sensitization of leukemia cells towards imatinib-induced apoptosis, suggesting that BGL3 acts as a tumor-suppressor in CML." (PMID 36362925, 2022). "In addition, SIRT1 is activated by the c-MYC oncogenic network in human FLT3-ITD+ AML leukemia stem cells (LSCs), which contributes to their maintenance and drug resistance." (PMID 35656547, 2022). "Methyltransferase 3(METTL3) increased the translation of downstream leukemia-related genes, such as MYC, BCL2, and PTEN mRNA, in an m6A-dependent manner, and depletion of METTL3 blocked proliferation, induced differentiation, and apoptosis in immunodeficient recipient mice." (PMID 35865470, 2022). "R-2HG, as a metabolite produced by mutant isocitrate dehydrogenases (IDHs), can inhibit FTO activity to increase the accumulation of m6A modified m6A in MYC transcripts of sensitive leukemia cells, resulting in decreased stability of MYC mRNA and downregulation of MYC signaling pathway." (PMID 35590394, 2022). "Thus, it is unlikely that the inability of MYC alone to induce leukemia under these experimental conditions is due to immune suppression of the cells expressing human transgenes." (PMID 34310280, 2021). "Although one recipient mouse of MYC-transduced HPCs became sick and was sacrificed approximately 150 days after transplantation, it did not exhibit any leukemia-associated signs." (PMID 34310280, 2021). "Furthermore, MLL-AF10 activated both the HOXA9 high and MYC high signature genes to induce leukemia while ectopic expression of HOXA9 and MYC synergistically induced leukemia." (PMID 34310280, 2021). "Indeed, co-expression of HOXA9, BCL2, or SOX4 promoted MYC-mediated leukemogenesis, while MYC alone was insufficient to induce leukemia in vivo." (PMID 34310280, 2021). "FACS analysis indicated that all of MYC/SOX4-induced leukemias were of myeloid lineage." (PMID 34310280, 2021).
leukemia (continued). "The most significantly downregulated signatures shared by those leukemia patients are E2F targets, DNA repairs, reactive oxygen species pathway, MYC targets and G2M checkpoint, indicating reduced cell cycle checkpoint and decreased DNA repair activities play an important role in leukemia." (PMID 33408321, 2021). "In addition, echinomycin decreased MYC and HIF1α protein levels in leukemia cell line THP1 from hematologic malignancies as well." (PMID 33572152, 2021). "Among the HOXA9 target genes, BCL2 and SOX4 synergistically induced leukemia with MYC." (PMID 34310280, 2021). "This additional MYC activity may be required to achieve sufficient leukemogenic ability, therefore MYC/HOXA9-transduced cells were able to induce leukemia in vivo." (PMID 34310280, 2021). "Accordingly, HOXA9 and MYC synergistically induce leukemia in mouse models." (PMID 34310280, 2021). "Furthermore, METTL14 is highly expressed in acute myelocytic leukaemia (AML) and can promote the occurrence of AML by inhibiting the degradation of MYB and MYC mRNA, promoting its translation and maintaining the self-renewal of leukaemia stem cells." (PMID 34900689, 2021). "Surprisingly, the restoration of miR-24 expression in TCF3-rearranged leukemic cell lines neither affects the expression of some of its targets nor alters the frequency of apoptotic cells, suggesting that MYC is regulated by a combination of mechanisms in this type of leukemia." (PMID 32102485, 2020). "Moreover, several findings have shown that BRG1 is needed for leukemia cell propagation, preserving a phenotype that controls MYC proto-oncogene expression." (PMID 33081305, 2020). "Finally, and similarly to the mechanism reported for BCR-ABL1-rearranged leukemia, MYC is also stabilized at the protein level through aberrantly altered phosphorylation at the Thr58 and Ser62 residues." (PMID 32102485, 2020). "The current hypothesis for the effect of BRD4 inhibitor treatment against leukemia is that the action of key developmental transcription factors, such as MYC, is blocked upon BRD4 inhibition." (PMID 32382029, 2020). "The aim of the study was to evaluate CEBPA and c-MYC mRNA expression level and to seek their association with demographical and clinical features of AML patients such as: age, gender, FAB classification, mortality or leukemia cell karyotype." (PMID 33170359, 2020). "Various studies suggest that c-MYC gene is dysregulated in cancers, including leukemias." (PMID 33170359, 2020). "Furthermore, mechanistic studies showed that in Ph+ B cell progenitors, BCR-ABL1 and LYN kinases phosphorylated γ-catenin at different sites, and only the phosphorylated protein induced MYC expression and promoted leukemia growth." (PMID 32806528, 2020). "In the following sections, we describe the role of MYC in several types of leukemia." (PMID 32102485, 2020). "Besides, leukemia also display at a high frequency an up-regulation of the c-MYC proto-oncogene that supports proliferation and survival." (PMID 33240808, 2020). "At the molecular level, our comparative transcriptomic analysis unveiled that BETi and THZ1 could synergistically suppress the transcription of oncogenes (e.g., MYC) under the control of enhancers in BETi-resistant leukemia." (PMID 32029739, 2020).